MIR557 (microRNA 557)
Synonyms: hsa-mir-557; MIRN557
Gene: MicroRNA gene on chromosome 1 (168,375,524 to 168,375,621, forward strand). Ensembl gene ENSG00000207974.
Gene Ontology:
Biological process: miRNA-mediated post-transcriptional gene silencing